CSRP2 (cysteine and glycine rich protein 2)
Description:
Drastically down-regulated in response to PDGF-BB or cell injury, that promote smooth muscle cell proliferation and dedifferentiation. Seems to play a role in the development of the embryonic vascular system.
Synonyms: CRP2; SmLIM; LMO5
Tractability: PROTAC: UniProt records ubiquitination sites on it; ubiquitination databases record sites on it.
Gene: Protein-coding gene on chromosome 12 (76,858,703 to 76,879,638, reverse strand). Ensembl gene ENSG00000175183.
Subcellular location: Nucleus
Gene Ontology:
Molecular function: protein binding; actinin binding; structural constituent of muscle
Biological process: cell differentiation; muscle tissue development; sarcomere organization
Cellular component: focal adhesion; cytoplasm; nucleus; Z disc
Genetic constraint (gnomAD): Loss-of-function variants: 15 observed, 22.75 expected, observed/expected ratio (o/e) 0.66, 90% interval 0.44 to 1.01. The upper end of that interval is the gene's LOEUF score, 1.01, which puts it in group 4 of 6, group 1 being the genes least tolerant of losing a copy. Missense variants: 214 observed, 244.51 expected, observed/expected ratio (o/e) 0.88, 90% interval 0.78 to 0.98. Synonymous variants: 87 observed, 85.48 expected, observed/expected ratio (o/e) 1.02, 90% interval 0.86 to 1.22.
Homologues: Orthologues: chimpanzee CSRP2 (100% identical), macaque CSRP2 (100% identical), mouse Csrp2 (99% identical), rat Csrp2 (99% identical), guinea pig CSRP2 (98% identical), pig CSRP2 (98% identical), tropical clawed frog csrp2 (88% identical), zebrafish csrp2 (87% identical), Drosophila melanogaster Mlp84B (51% identical), Drosophila melanogaster Mlp60A (50% identical), dog CSRP2 (46% identical), Caenorhabditis elegans mlp-1 (24% identical). Paralogues in human: CSRP1 (79% identical), CSRP3 (66% identical).
Diseases named in the same sentence as CSRP2 in open-access papers:
CSRP2 is named in the same sentence as 37 diseases in open-access papers, as found by Europe PMC text mining. Sharing a sentence is not in itself a finding about the gene and the disease. The quoted sentences say what the papers report.
breast carcinoma (8 papers, 2016 to 2025). "High CSRP2 mRNA expression was significantly associated with reduced overall survival for breast cancer patients." (PMID 29976963, 2018). "A microarray-based analysis identified the CRP2 encoding gene, CSRP2, in a cluster of 14 genes whose high expression is characteristic of basal-like breast carcinoma, a breast cancer subtype associated with poor prognosis." (PMID 26883198, 2016). "Finally, we found that CSRP2 up-regulation correlates with hypoxic regions in both pre-clinical and clinical breast tumour specimens, and is associated with poor prognosis in breast cancer patients." (PMID 29976963, 2018). "In microarray-based analyses high-expression of CSRP2 is associated with basal-like breast cancer." (PMID 28415593, 2017). "In addition, high expression of the CRP2 encoding gene CSRP2 was associated with significantly increased risk of metastasis in basal-like breast cancer patients." (PMID 26883198, 2016). "CSRP2 is involved in tumor cell proliferation, migration, and invasion in breast cancer, gastric cancer, and lymphocytic leukemia." (PMID 37964257, 2023). "Collectively our data indicate that CSRP2 an important mediator of hypoxia-stimulated invadopodium formation in breast cancer cells." (PMID 29976963, 2018). "Overall, our data point to an important role for CSRP2 in facilitating the pro-invasive and -metastatic effects of hypoxia in breast cancer." (PMID 29976963, 2018). "Accordingly, CSRP2 knockdown significantly inhibits invadopodium formation in aggressive breast cancer cells, as well as MMP secretion and 3D matrix invasion." (PMID 29976963, 2018). "The four breast cancer cell lines we analyzed responded to experimental hypoxia by increasing CSRP2 mRNA and protein expression." (PMID 29976963, 2018). "In the four breast cancer cell lines, hypoxia induced a significant and sustained elevation of CSRP2 transcripts, suggesting that CSRP2 levels were regulated at the transcriptional level." (PMID 29976963, 2018). "Here, we show that CSRP2, an invadopodial actin bundling protein, is upregulated by hypoxia in various breast cancer cell lines, as well as in pre-clinical and clinical breast tumour specimens." (PMID 29976963, 2018). "To more directly evaluate CSRP2 up-regulation in hypoxic areas of human breast tumours, we conducted immunohistochemical analyses of clinical breast cancer specimens." (PMID 29976963, 2018). "Here, we identified a novel mechanism by which hypoxia promotes mesenchymal invasion in breast cancer cells through the upregulation of CSRP2, a structural component of the actin cytoskeleton machinery involved in invadopodium formation." (PMID 29976963, 2018). "Collectively, these data suggest that hypoxia promotes invadopodia-mediated breast cancer cell invasion by upregulating CSRP2, a basic component of the invadopodial actin cytoskeleton machinery." (PMID 29976963, 2018). "Taken all together, our data suggest that tumour hypoxia promotes CSRP2 overexpression, exacerbating the clinical outcome of breast cancer patients by enhancing tumour cell invasion and subsequent spread to distant tissues." (PMID 29976963, 2018). "Increased CSRP2 transcription also promotes migration of breast cancer cells via an actin bundling factor." (PMID 28415593, 2017). "An in silico analyses using publicly available gene expression datasets reported worse survival of women with the basal-like subtype of breast cancer with high expression of CSRP2." (PMID 28415593, 2017). "Knockdown of CSRP2 significantly inhibited the invasion of breast cancers, the proliferation of desmoid tumors, and the migration and invasive ability of head and neck squamous cell carcinoma cells, and increased drug sensitivity in acute lymphoblastic leukemia." (PMID 40764945, 2025). "Although the specific functions of CSRP2 in breast cancer, colorectal cancer and B-cell ALL may differ, these studies all point to the deleterious clinical consequence of CSRP2 overexpression." (PMID 29976963, 2018).
breast carcinoma (continued). "Comparison of CSRP2 expression in different breast cancer subtypes revealed that CSRP2 expression is an order of magnitude higher in the basal subtype, compared to the other subtypes and, accordingly, is a stronger predictor of distant metastasis-free survival." (PMID 29976963, 2018). "We assessed the effects of hypoxia on the expression of the pro-invasive and -metastatic invadopodial protein CSRP2 in four breast cancer cell lines, including luminal/epithelial-like MCF-7 and T47D (ER+, PR+), and mesenchymal-like MDA-MB-231 and Hs578T (ER−, PR−, HER2−, claudin-low)." (PMID 29976963, 2018). "Collectively, our data indicate that hypoxia exerts a direct control on invadopodium-mediated tumour cell invasion through HIF-1-mediated upregulation of the actin-bundling protein CSRP2 and provide a new mechanistic basis for the pro-metastatic effects of tumour hypoxia in breast cancer." (PMID 29976963, 2018). "Besides its role in breast cancer, CSRP2 was recently identified as a downstream target of H19, the long non-coding RNA with the strongest association with colorectal cancer patient survival." (PMID 29976963, 2018). "Consistent with ChIP and luciferase reporter data, CSRP2 and HIF-1α protein levels were significantly correlated in both pre-clinical and patient tumour specimens, supporting that tumour hypoxia is an important determinant of CSRP2 up-regulation in breast cancer." (PMID 29976963, 2018). "CSRP2 is a possible oncogene in hepatocellular carcinoma and breast cancer." (PMID 28415593, 2017). "However, the function of CSRP2 in different tumors is controversial, for example, CSRP2 was found to promote invasion and metastasis in breast cancer and chemoresistance in leukemia, but inhibit proliferation, migration, and invasion in gastric and colon cancers." (PMID 40764945, 2025). "Kaplan-Meier and logrank tests revealed that, within the basal-like subtype, breast cancer patients with higher expression of CSRP2 in the primary tumor exhibit significantly reduced metastasis-free survival as compared to patients with lower expression of CSRP2 (HR = 1.98, P = 0.01)." (PMID 26883198, 2016). "Although there is limited information on the role of CSRP2 in cancers, few studies suggested that it plays an important role in some cancers, such as gastric cancer, HCC and breast cancer 9-11." (PMID 33042270, 2020). "Cysteine-rich protein 2 (CSRP2), as a novel target of HIF-1α, attributes to breast cancer cell invasion under hypoxic conditions by regulating the formation of invadopodium actin backbone." (PMID 32215176, 2020). "Of note, CSRP2, which is an invadopodia actin-bundling protein that is upregulated by hypoxia (HIF-1α) in various breast cancer cell lines and tumors, is also upregulated in MKL1 ΔN200 cells." (PMID 32699630, 2020). "Noticeably, fascin and CSRP2 knockdown achieves comparable reduction in ECM degradation and 3-D invasion in invasive breast cancer cells, suggesting a functional interaction/redundancy between these two actin bundling proteins." (PMID 29976963, 2018). "To strengthen this conclusion, we validated the role of CSRP2 in facilitating hypoxia-stimulated invadopodia formation, ECM degradation and cell invasion in another invasive breast cancer cell line, namely the mouse 4T1 cell line." (PMID 29976963, 2018). "Collectively, our data support that CSRP2 is a novel and direct cytoskeletal target of HIF-1 which facilitates hypoxia-induced breast cancer cell invasion by promoting invadopodia formation." (PMID 29976963, 2018). "In the present study, we show that hypoxia upregulates CSRP2 in different breast cancer cell lines, and that such upregulation results from HIF-1-mediated transactivation of the CSRP2 promoter." (PMID 29976963, 2018). "We provide evidence that CSRP2 depletion strongly reduces the ability of hypoxia to enhance invadopodia formation, ECM degradation and invasion in highly invasive breast carcinoma cell lines, such as MDA-MB-231 and mouse 4T1." (PMID 29976963, 2018).
breast carcinoma (continued). "CSRP2 is thought to inhibit the invasion and metastasis of cancer cells in gastric cancer and may be related to the progression and dedifferentiation of HCC, but has an opposite role in breast cancer." (PMID 33042270, 2020).
gastric cancer (6 papers, 2020 to 2023). A primary or metastatic malignant neoplasm involving the stomach. "miR-27a is expressed at high levels in the EVs of gastric cancer cell-derived EVs and inhibits CSRP2 in recipient fibroblasts, resulting in CAF differentiation, and increased proliferation and migration." (PMID 32957712, 2020). "Exosomal miR-27a derived from gastric cancer (GC) is transported to fibroblasts, and thus results in decreased expression of CSRP2, enhanced expression of α-SMA, and differentiation of fibroblasts into CAFs." (PMID 32299469, 2020).
B-cell acute lymphoblastic leukemia (4 papers, 2017 to 2025). A neoplasm of lymphoblasts committed to the B-cell lineage, typically composed of small to medium-sized blast cells. "Cysteine and glycine-rich protein 2 (CSRP2) is upregulated in B cell acute lymphoblastic leukemia (B-ALL)." (PMID 40959280, 2025).
colorectal cancer (4 papers, 2018 to 2025). A primary or metastatic malignant neoplasm that affects the colon or rectum. "Previous studies noticed the interaction between CSRP2 and p130Cas in mouse vascular smooth muscle and in colorectal cancer." (PMID 40764945, 2025). "The progression of colorectal cancer can be suppressed by CSRP2 via ERK, PAK, and HIPPO signaling pathways in vitro." (PMID 34585646, 2021). "A previous study reported lower expression of CSRP2 in colorectal cancer tissues than in normal tissues." (PMID 34585646, 2021). "Since it was reported that CSRP2 interacted with p130Cas in mouse vascular smooth muscle and in colorectal cancer, we explored whether CSRP2 interacts with p130Cas in GBM." (PMID 40764945, 2025). "However, knockdown of CSRP2 promoted the malignant progression of gastric and colorectal cancers." (PMID 40764945, 2025).
leukemia (4 papers, 2009 to 2025). A malignant (clonal) hematologic disorder, involving hematopoietic stem cells and characterized by the presence of primitive or atypical myeloid or lymphoid cells in the bone marrow and the blood. "One is the indication of more residual leukemia cells compared with subjects with low CSRP2 expression." (PMID 37183704, 2023). "The overexpression of CSRP2 in MLL mutated samples distinguishing ALL and AML supports a novel role for CSRP2 gene in leukemia development." (PMID 19549311, 2009). "Deregulation events of CSRP2, TCL1A, CD72 and EBF genes in acute pediatric leukaemia have been previously reported using gene expression profiling." (PMID 19549311, 2009).
hepatocellular carcinoma (3 papers, 2017 to 2025). A malignant tumor that arises from hepatocytes. "Increased CSRP2 transcript levels are associated with dedifferentiation in hepatocellular carcinoma." (PMID 28415593, 2017). "CSRP2 has been studied in several tumors, including breast 9, gastric 10, hepatocellular cancers 11 and lymphoblastic leukemia 6 and is involved in the proliferation, migration and invasion of tumor cells." (PMID 33042270, 2020). "CSRP2 expression was also found increased in hepatocellular carcinoma." (PMID 40764945, 2025).
glioma (2 papers, 2025). A benign or malignant brain and spinal cord tumor that arises from glial cells (astrocytes, oligodendrocytes, ependymal cells). "CSRP2 expression in low-grade and high-grade gliomas was analyzed, and survival analyses were performed in patients with gliomas with high and low CSRP2 expression in various tumor databases." (PMID 40764945, 2025). "We found that CSRP2 expression significantly increased in GBM, especially mesenchymal GBM, and that glioma patients with high CSRP2 expression possibly had poor prognosis." (PMID 40764945, 2025). "To investigate the function of CSRP2 in GBM, we infected two glioma cell lines (U87-MG and U251) with lentiviruses overexpressing CSRP2 or control, and obtained stable cell lines after puromycin selection." (PMID 40764945, 2025). "To investigate whether CSRP2 is involved in the malignant progression of gliomas, we first analyzed CSRP2 expression using data from TCGA, GEPIA, Gravendeel, Rembrandt, and CGGA databases." (PMID 40764945, 2025). "Two very recent studies reported that CSRP2 could maintain the malignant phenotypes of gliomas through the Notch signaling pathway and inhibit glioma necroptosis through activating the JAK-STAT1 signaling pathway." (PMID 40764945, 2025). "Very recently, two studies reported that CSRP2 could maintain the malignant phenotypes of gliomas through the Notch signaling pathway and inhibit glioma necroptosis through activating the JAK-STAT1 pathway." (PMID 40764945, 2025). "In addition, cysteine- and glycine-rich protein 2 (CSRP2) is consistently overexpressed in glioma tissues and cell lines, where it drives malignant progression through dual oncogenic mechanisms." (PMID 41267084, 2025). "We found that CSRP2 expression significantly increased in both low-grade glioma (LGG) and GBM tissues when compared to normal tissues, and CSRP2 expression was higher in GBM with advanced pathological grades than those with low pathological grades." (PMID 40764945, 2025).
Hepatic fibrosis (2 papers, 2006 to 2016). The presence of excessive fibrous connective tissue in the liver. "Chronic liver injury causes activation of hepatic stellate cells leading to hepatic fibrosis, and both Lhx2 and Csrp2 have been negatively implicated in this process, suggesting overlapping function of these genes also in non-hematopoietic cells." (PMID 16600034, 2006).
asthma (1 paper, 2025). "Upregulation of Csrp2 inhibits the PDGF-BB-induced transition of ASMCs to a synthetic/proliferative phenotype via modulation of the Yes-associated protein (YAP)/transcriptional coactivator with PDZ-binding motif (TAZ) signaling axis, thereby contributing to airway remodeling in asthma." (PMID 40771395, 2025).
atherosclerosis (1 paper, 2025). A disease characterized by the build-up of fatty material and calcium deposition in the arterial wall resulting in partial or complete occlusion of the arterial lumen. "We identified 12 lactylation-related genes that are more reliably associated with atherosclerosis: five upregulated genes (LSP1, IKZF1, MNDA, RCC2, and WAS) and seven downregulated genes (CSRP2, PPP1CB, CSRP1, HEXIM1, CALD1, PDLIM1, and RANBP2)." (PMID 40248193, 2025).
brain tumor (1 paper, 2025). "Finally, we collected clinical samples from 4 non-brain tumor patients and 4 GBM cases for analysis, found that both mRNA and protein levels of CSRP2 were significantly higher in GBM than controls." (PMID 40764945, 2025).
cardiac hypertrophy (1 paper, 2022). "Although mice lacking Csrp2 survive, they exhibit cardiac hypertrophy." (PMID 36388115, 2022).
colorectal tumours (1 paper, 2018). "Patients with high CSRP2 expression in colorectal tumours, display significantly shorter overall survival, and combined analysis of H19 with CSRP2 appears to be a powerful prognostic factor for overall survival." (PMID 29976963, 2018).
glioblastoma (1 paper, 2025). The most malignant astrocytic tumor (WHO grade IV). "However, whether and how CSRP2 participates in the malignancy of glioblastoma multiforme (GBM), including its proneural-to-mesenchymal transition (PMT), remains unclear." (PMID 40764945, 2025).
head and neck squamous cell carcinoma (1 paper, 2021). A squamous cell carcinoma that arises from any of the following anatomic sites: lip and oral cavity, nasal cavity, paranasal sinuses, pharynx, larynx, and salivary glands. "In head and neck squamous cell carcinoma (HNSCC), the high expression of CSRP2 implied a better prognosis, which is highly consistent with our results." (PMID 34585646, 2021).
liver cancer (1 paper, 2025). An epithelial or non-epithelial malignant neoplasm that arises from the liver. "Clinical translational analysis revealed that Csrp2 demonstrates superior diagnostic efficacy (AUC >0.8) in HCC tissues compared to conventional biomarker AFP, with its peripheral blood detection technology showing promise for non-invasive early screening of liver cancer." (PMID 41323394, 2025). "qPCR validation in normal liver and HCC tissues showed that CCNA2, CSRP2, ILF2, KIF2C, RACGAP1, and VARS were significantly upregulated in the HCC group (all p-values < 0.0001), providing more evidence for their role in liver cancer progression and potential as HCC biomarkers." (PMID 41323394, 2025).
lymphoma (1 paper, 2017). A malignant (clonal) proliferation of B- lymphocytes or T- lymphocytes which involves the lymph nodes, bone marrow and/or extranodal sites. "CSRP2 maps to 12q21 which is reported abnormal in haematological neoplasms including T-cell ALL and lymphoma." (PMID 28415593, 2017).
oral squamous cell carcinoma (1 paper, 2023). "CSRP2 is associated with a better prognosis in oral squamous cell carcinoma." (PMID 37964257, 2023).
osteoporosis (1 paper, 2025). A condition of reduced bone mass, with decreased cortical thickness and a decrease in the number and size of the trabeculae of cancellous bone (but normal chemical composition), resulting in increased fracture incidence. "CSRP2 and FUBP1 can serve as biomarkers for the early prediction of osteoporosis risk in individuals with low BMD/PBM." (PMID 40927289, 2025). "CSRP2 and FUBP1 can serve as biomarkers for the early prediction of osteoporosis risk in individuals with low peak bone mass or bone mineral density." (PMID 40927289, 2025).